IGKV1D-17 (immunoglobulin kappa variable 1D-17)
Description:
V region of the variable domain of immunoglobulin light chains that participates in the antigen recognition. Immunoglobulins, also known as antibodies, are membrane-bound or secreted glycoproteins produced by B lymphocytes. In the recognition phase of humoral immunity, the membrane-bound immunoglobulins serve as receptors which, upon binding of a specific antigen, trigger the clonal expansion and differentiation of B lymphocytes into immunoglobulins-secreting plasma cells. Secreted immunoglobulins mediate the effector phase of humoral immunity, which results in the elimination of bound antigens. The antigen binding site is formed by the variable domain of one heavy chain, together with that of its associated light chain. Thus, each immunoglobulin has two antigen binding sites with remarkable affinity for a particular antigen. The variable domains are assembled by a process called V-(D)-J rearrangement and can then be subjected to somatic hypermutations which, after exposure to antigen and selection, allow affinity maturation for a particular antigen.
Synonyms: IGKV1D17; L14
Gene: Immunoglobulin variable (V) gene on chromosome 2 (90,082,635 to 90,083,291, forward strand). Ensembl gene ENSG00000242766.
Subcellular location: Secreted; Cell membrane
Gene Ontology:
Biological process: immune response
Cellular component: extracellular region; immunoglobulin complex; plasma membrane
Homologues: Orthologues: mouse Igkv15-103 (70% identical). Paralogues in human: IGKV1-17 (91% identical), IGKV1-16 (90% identical), IGKV1-9 (89% identical), IGKV1-12 (88% identical), IGKV1-6 (87% identical), IGKV1D-12 (87% identical), IGKV1D-16 (87% identical), IGKV1-27 (86% identical), IGKV1D-13 (86% identical), IGKV1-39 (85% identical), IGKV1D-39 (85% identical), IGKV1-5 (85% identical), and 81 more.
Diseases named in the same sentence as IGKV1D-17 in open-access papers:
IGKV1D-17 is named in the same sentence as 1 disease in open-access papers, as found by Europe PMC text mining. Sharing a sentence is not in itself a finding about the gene and the disease.
IGKV1D-17 shares sentences with these, for which no sentence is quoted: adenoma (1 paper).